RNU6-251P (RNA, U6 small nuclear 251, pseudogene)
Gene: Small nuclear RNA gene on chromosome 12 (15,671,707 to 15,671,810, reverse strand). Ensembl gene ENSG00000200105.
Homologues: Orthologues: macaque U6 (94% identical), rabbit U6 (91% identical), dog U6 (82% identical), guinea pig U6 (74% identical). Paralogues in human: RNU6-19P (90% identical), RNU6-12P (89% identical), RNU6-13P (89% identical), RNU6-24P (89% identical), RNU6-26P (89% identical), RNU6-31P (89% identical), RNU6-32P (89% identical), RNU6-737P (89% identical), RNU6-949P (89% identical), RNU6-1 (88% identical), RNU6-1024P (88% identical), RNU6-1060P (88% identical), and 1289 more.